TMED4 (transmembrane p24 trafficking protein 4)
Description:
Involved in vesicular protein trafficking, mainly in the early secretory pathway. targeting. Involved in the maintenance of the Golgi apparatus. Appears to play a role in the biosynthesis of secreted cargo including processing. Involved in endoplasmic reticulum stress response. May play a role in the regulation of heat-shock response and apoptosis (By similarity).
Synonyms: ERS25; p24alpha3; HNLF; p24a3; GMP25iso
Tractability: Antibody: UniProt predicts a signal peptide or a membrane-spanning region. PROTAC: ubiquitination databases record sites on it; its protein half-life has been measured.
Gene: Protein-coding gene on chromosome 7 (44,576,392 to 44,582,287, reverse strand). Ensembl gene ENSG00000158604.
Subcellular location: Endoplasmic reticulum membrane
Gene Ontology:
Biological process: positive regulation of canonical NF-kappaB signal transduction; endoplasmic reticulum to Golgi vesicle-mediated transport; Golgi organization
Cellular component: endoplasmic reticulum-Golgi intermediate compartment; endoplasmic reticulum membrane
Genetic constraint (gnomAD): Loss-of-function variants: 17 observed, 19.7 expected, observed/expected ratio (o/e) 0.86, 90% interval 0.59 to 1.29. The upper end of that interval is the gene's LOEUF score, 1.29, which puts it in group 5 of 6, group 1 being the genes least tolerant of losing a copy. Missense variants: 246 observed, 240.86 expected, observed/expected ratio (o/e) 1.02, 90% interval 0.92 to 1.13. Synonymous variants: 98 observed, 93.85 expected, observed/expected ratio (o/e) 1.04, 90% interval 0.89 to 1.24.
Homologues: Orthologues: chimpanzee TMED4 (99% identical), macaque TMED4 (98% identical), mouse Tmed4 (95% identical), rabbit TMED4 (94% identical), guinea pig TMED4 (92% identical), pig TMED4 (91% identical), zebrafish tmed4 (81% identical), tropical clawed frog tmed4 (79% identical), rat Tmed4 (75% identical), Drosophila melanogaster eca (65% identical), Drosophila melanogaster p24-2 (59% identical), Caenorhabditis elegans tmed-12 (40% identical). Paralogues in human: TMED9 (77% identical), TMED10 (33% identical), TMED7 (26% identical), TMED3 (23% identical), TMED2 (22% identical), TMED6 (22% identical), TMED5 (22% identical), TMED1 (21% identical).
Diseases named in the same sentence as TMED4 in open-access papers:
TMED4 is named in the same sentence as 15 diseases in open-access papers, as found by Europe PMC text mining. Sharing a sentence is not in itself a finding about the gene and the disease. The quoted sentences say what the papers report.
colorectal cancer (1 paper, 2024). A primary or metastatic malignant neoplasm that affects the colon or rectum. "Additionally, a positive correlation was identified between TMED1 and other members of the TMED family (TMED2, TMED4, TMED9, and TMED10) in colorectal cancer." (PMID 38392302, 2024).
dilated cardiomyopathy (1 paper, 2023). Cardiomyopathy which is characterized by dilation and contractile dysfunction of the left and right ventricles. "A Pakistani study identified a deleterious variant of TMED4 that resulted in gene overexpression in myocardial tissue of patients with dilated cardiomyopathy, suggesting a possible involvement of TMED4 in myocardial dilatation." (PMID 37928880, 2023).
mild cognitive impairment (1 paper, 2025). "Numerous TMED proteins have been shown to be dysregulated in mild cognitive impairment (MCI) and AD brains: While TMED5 expression increases in the AD parietal cortex, expression of both TMED4 and TMED9 decreases in the AD frontal cortex." (PMID 41103078, 2025).
tumor (3 papers, 2023 to 2025). "When TMED4 is depleted, Treg cells promote the activation of effector T cells in mouse tumor models, thereby enhancing the body's antitumor immunity." (PMID 41391769, 2025). "Correspondingly, we found a significant positive correlation between upregulation of TMED4 and activation of the antioxidant response in the tumor microenvironment, as obtained from TCGA datasets." (PMID 39480507, 2024). "Recent studies have shown that TMED4 also plays an important role in tumor occurrence and development." (PMID 37171335, 2023). "Additionally, we carried out in vivo rescue experiments in which WT or Tmed4-deficient CD45.2+ Tregs pretreated with DMSO and NAC, respectively, were inoculated into MC38 tumor cell–bearing CD45.1+ mice." (PMID 39480507, 2024). "The absence of TMED4 facilitates the conversion of Tregs to Teff cells, enhancing T cell activation and antitumor immunity in the MC38 tumor model." (PMID 39480507, 2024).
TMED4 also shares sentences with these, for which no sentence is quoted: autoimmune disease (1 paper); cancer (1); colon adenocarcinoma (1); gastric cancer (1); glioma (1); hepatocellular carcinoma (1); lung adenocarcinoma (1); lung carcinoma (1); rectal adenocarcinoma (1); SARS-CoV infection (1); stomach adenocarcinoma (1).